UPK1A-AS1 (UPK1A antisense RNA 1)
Gene: Long non-coding RNA gene on chromosome 19 (35,667,943 to 35,673,509, reverse strand). Ensembl gene ENSG00000226510.
Diseases named in the same sentence as UPK1A-AS1 in open-access papers:
UPK1A-AS1 is named in the same sentence as 1 disease in open-access papers, as found by Europe PMC text mining. Sharing a sentence is not in itself a finding about the gene and the disease. The quoted sentences say what the papers report.
esophageal squamous cell carcinoma (1 paper, 2022). Esophageal squamous cell carcinoma (ESCC) is a type of esophageal carcinoma (EC) that can affect any part of the esophagus, but is usually located in the upper or middle third. "In esophageal squamous cell carcinoma (ESCC), miR-1248 decreased expression by UPK1A antisense RNA 1 lncRNA sponging resulted in suppressed cellular proliferation, migration and invasion, further indicating its oncogenic role." (PMID 35715818, 2022).